EGFR (epidermal growth factor receptor)
Diseases named in the same sentence as EGFR in open-access papers (continued):
Sharing a sentence is not in itself a finding about the gene and the disease.
tumor (continued). "If OS is the primary goal in RAS wild-type right-sided tumours with a widely disseminated disease not amenable to surgery, anti-EGFR substances may be discussed but are not the primary choice." (PMID 33154570, 2021). "However, EGFR inhibition is not always detrimental for tumor progression as the significant level of acute tumor cell death associated with EGFR inhibition induces compensatory HCC proliferation." (PMID 34633987, 2021). "Furthermore, expression of EGFR and its ligands may be promoted by ADAMs activation, as was studied in GIST tumor samples, implying an important role of the EGFR pathway for GIST oncogenesis." (PMID 33419029, 2021). "As previously reported, multiplex sequencing of tumour samples from patients with gastroesophageal cancer is feasible and does identify potentially actionable targets, in most cases amplification of known oncogenes such as ERBB2, EGFR, FGFR1–3, KRAS and MET, in a significant proportion of patients." (PMID 34794033, 2021). "Indeed, similarly to EGFR exon 20 insertions, they are usually found in younger patients, never smokers, and in patients with a smaller tumor size." (PMID 33807876, 2021). "Therefore, we shed light on the effect of RA on ADAM17 expression and found that RA considerably inhibited the expression of ADAM17 together with the downstream mediators of ADAM17, which constitutes ADAM17/EGFR/AKT/GSK3β axis and represents a crucial pathway for tumor progression." (PMID 34224305, 2021). "These biological targets (e.g., receptor tyrosine kinases EGFR, c-Met, and non-receptor tyrosine kinase c-Src) are known to synergistically potentiate each other’s effects in driving tumor growth and provide a strong rationale for developing a multi-targeted approach against their adverse effects." (PMID 34502481, 2021). "Thus, although cetuximab exerted an anti-tumor effect in EGFR-overexpressed MDA-MB-468 cells, this effect was not accomplished by inducing pyroptosis." (PMID 33472170, 2021). "In support of our hypothesis that EGFR overexpression may lead to TGFβ activation, preliminary data from our lab suggested an increased release of bioactive TGFβ from tumour cell lines transgenically overexpressing mutant forms of EGFR (data not shown)." (PMID 35052732, 2021). "The odds ratio of ORR favored anti-EGFR-based chemotherapy regardless of the primary tumor location (OR: 1.49, 95% CI=1.16–1.0, p=0.002 for left-sided tumor; OR: 1.2, 95% CI= 0.77–1.87, p=0.432 for right-sided tumor) compared to anti-VEGF-based chemotherapy." (PMID 34868987, 2021). "Notably, MDA-MB-453 tumor cells in vitro do not come with an EGFR gene amplification and do not express EGFR (analyzed by FISH and western blotting; unpublished data)." (PMID 34070094, 2021). "Furthermore, one variant in EGFR, two in KRAS, and one in BRAF were detected in plasma but not in tumor samples." (PMID 34217228, 2021). "In addition, lack of fluorescence in an EGFR-positive tumor can reassure the surgeon that the deep margin and sentinel margin negative (margin that is likely to be negative) is truly negative with an appropriate margin distance." (PMID 34002555, 2021). "However, combination with co-stimulatory αCD28 BiMAb recognizing HER2, EpCAM, EGFR or PD-L1 significantly enhanced the anti-tumor immune response compared to no-antibody controls as well as to single treatment with αHER2–αCD3." (PMID 34484225, 2021). "In order to determine whether EGFR inhibiton can directly block lung colonization of TN1 PDX cells in vivo, LA1 was also directly administered to the recipient mice along with tumor cell injection as well as 2 days after tumor cell infusion." (PMID 33995681, 2021).
tumor (continued). "Biomarkers like KRAS, EGFR, MET, HER2 or PIK3CA were also accurately distinguished using surrogate TEP mRNA profiles as well as EML4-ALK rearrangements.Other studies have also shown that the analysis of mRNA profiles may allow to detect the primary tumor." (PMID 33937034, 2021). "We hypothesised that anti-EGFR treatment is most effective when added to an oxaliplatin backbone in patients with CMS2/3 tumours in the COIN trial, while patients with mesenchymal CMS4 benefit most from anti-EGFR added to an irinotecan backbone as given in the PICCOLO trial." (PMID 34253874, 2021). "Sokolov and co-workers have developed an EGFR-targeted AuNPs for active targeting PAI, and demonstrated that 5 nm AuNPs could work as well as the 40 nm AuNPs with a comparable PA signal, but 5 nm AuNPs showed outstanding tumor penetration and clearance." (PMID 33920453, 2021). "However, RICTOR activation is linked to resistance to receptor tyrosine kinase inhibitors and RICTOR interacts with EGFR independent of its kinase activity in other tumor entities." (PMID 34771501, 2021). "Thus, any negative regulator of the EGFR, such as EGFRAP and PVRAP, could act as tumor suppressors of the overgrowth of wild type cells ectopically expressing RasV12." (PMID 34411095, 2021). "Thus, cinobufagin inhibits EGFR and STAT3 signaling to block tumor growth in nude mice." (PMID 34925034, 2021). "Based on the promising efficacy, in 2021, the U.S. FDA granted tiragolumab BTD in combination with atezolizumab (Tecentriq) for the first‐line treatment of individuals with metastatic NSCLC whose tumors have PD‐L1 expression ≥50% and no EGFR or ALK genomic tumor aberrations." (PMID 34977873, 2021). "Our findings collectively demonstrate that Pgrmc1 plays a tumor-promoting function in non-parenchymal cells through the modulation of EGFR expression and may serve as a potential target for treating HCC." (PMID 34069911, 2021). "SPECT images revealed that the 99mTc-labeled nanobodies could specifically recognize tumor cells expressing EGFR, distinguishing them from non-tumor cells and minimizing falsity in the results." (PMID 33925941, 2021). "On the contrary, YTHDF2 was reported to function as a tumor suppressor in other studies, YTHDF2 inhibited the proliferation and growth of HCC cells via promoting the degradation of epidermal growth factor receptor (EGFR) mRNA, which is the upstream of the ERK/MAPK pathway." (PMID 33928028, 2021). "Through studies using human cancer cell line derived xenografts, the remarkable anti-tumour activity of tarloxotinib was also established in NSCLC and squamous cell carcinoma of the skin, and head and neck with nanomolar potency against both the wild-type and mutant EGFR." (PMID 33923305, 2021). "It was reported that the EGF-EGFR pathway was involved in the development of inflammatory microenvironment in HCC; EGF might facilitate DNA synthesis, regeneration, tumor growth, and progression of HCC cells and bind with EGFR as the potential connection between inflammation and HCC." (PMID 33688369, 2021). "While the VAFs associated with the originating tumors of the GBOS allow for hypothesizing of independent EGFR mutant tumor populations, one caveat is that the NGS methods used do not allow for concrete determination of subpopulations." (PMID 34568006, 2021). "Therefore, co-targeting of these two receptors using a BsAb may disrupt the autocrine and paracrine cooperation of EGFR/VEGFR2 signaling and inhibit tumor growth and survival in TNBC." (PMID 33804477, 2021). "Patients without EGFR CNG positive tumours had similar overall survival regardless of whether they received pre-operative PBC or not." (PMID 33169187, 2021). "Furthermore, in clinical trials, a lack of correlation between the efficacy of EGFR inhibitor treatment and EGFR expression levels of treated tumours was observed." (PMID 35052732, 2021).
tumor (continued). "In addition, silencing of EGFR significantly rescued FBXL2 knockdown-induced tumor growth in H292 xenograft mouse model, indicating that silencing of FBXL2 promotes NSCLC cell proliferation and tumor growth via up-regulation of EGFR expression." (PMID 34635651, 2021). "In situations of progression under EGFR-TKI, the better tumor sample to be used for molecular/histological analysis seems to be from the site of progression---tissue or cytological samples (i.e., pericarditis, pleural, and bronchoalveolar lavage)---if containing enough tumor cells." (PMID 34638411, 2021). "This approach uses a tumor-specific agent in combination with a non-targeted or perfusion agent to subtract nonspecific signals, thereby improving contrast and/or measuring extracellular EGFR regions." (PMID 34277418, 2021). "In pre-clinical studies, EGFR inhibition enhanced antigen presentation to T-cells, stimulated immunogenic apoptosis of tumor cells, boosted T-cell chemoattractants, and stimulated MHC-1 upregulation, all of which are predicted to enhance the anti-tumor immune response." (PMID 34868953, 2021). "However, limited oxygen supply and EGFR-expression were not always mutually exclusive since EGFR was also found in some hypoxic tumor areas." (PMID 33718186, 2021). "Among them, we mainly analyzed four genes (EGFR and BMP1 in ESCC and IL-1B and MAPT in EAC) that were related to gender, tumor stage, lymph node metastasis, distant metastasis, and other clinical features in EC, supposing that they might play essential roles in the prognosis of EC patients." (PMID 33859939, 2021). "Similarly, cetuximab enhanced the cytotoxic activity of NK cells on EGFR+ tumor cells independent of RAS status." (PMID 34178645, 2021). "Tumours harboring mutations in the RAS family (KRAS, NRAS, HRAS) result in constitutive activation of the MAPK signalling pathway, and are unlikely to benefit from treatment with epidermal growth factor receptor (EGFR) antibodies." (PMID 34073585, 2021). "Moreover, Elevated levels of N-cadherin and integrinβ could promote tumor cells adhesion to ECM, thereby, promoting EGFR TKI resistance." (PMID 33170304, 2021). "In short, uPAR typically binds to cell membrane surface proteins, such as integrin, EGFR and GPCR to promote cell proliferation, whereas binding of uPAR by its inhibitors leads to lysosome-mediated degradation of the uPAR, thus repressing of uPAR on the proliferation of tumor cells." (PMID 34729105, 2021). "Therefore, we engineered an epidermal growth factor receptor (EGFR) CAR-T cell to express a second receptor CXCR5, to facilitate migration of CAR-T cells to the CXCL13-expressing NSCLC tumors, and to minimize EGFR-CAR-T possible off-tumor, on-target toxicity." (PMID 34553036, 2021). "In addition, adequate evidence has shown that EGFR can directly phosphorylate β-catenin and stimulate EMT by disturbing the interaction between β-catenin and E-cadherin in tumor cells, leading to enhanced tumor spread." (PMID 34376211, 2021). "In the EGFR-mutant cell lines, the variable inhibitors of PI3K-AKT and MAPK-ERK presented variable antitumor activity, indicating that the ability of TKIs to eliminate tumor cells accounted for the inhibitor of survival signaling, including PI3K-AKT and MAPK-ERK." (PMID 34367939, 2021). "In the EGFR TKI-resistance patients Axl may activate downstream pathways inducing cell survival and growth, circumventing the need for EGFR activation, and suggesting that co-treatment of EGFR and Axl inhibitors may reduce tumour growth more effectively." (PMID 33806258, 2021). "Tumor uptake in MDA-MB-468 xenograft models was 15 ± 3.1% ID/g with T/B ratio of 12 ± 1.4 at 24 h p. i., indicating that 99mTc-PmFab-His6 is a promising probe for imaging EGFR and may be used to monitor the response to EGFR-directed therapies." (PMID 33986665, 2021).
tumor (continued). "Furthermore, neither tumor mutation burden nor co-occurring MET and EGFR mutations were significantly correlated with the size of the MET amplification." (PMID 34758872, 2021). "It has to be highlighted that EGFR T790M is not the only mechanism of resistance to first- and second-generation EGFR-TKIs, and it could not be detected even in a tumor re-biopsy." (PMID 34680416, 2021). "For the validation set of tumor samples from 19 independent NSCLC patients, we could observe a significantly lower abundance of CD8+ and CD103+CD8+ T cells in EGFR-MT compared with EGFR-WT." (PMID 34663810, 2021). "Moreover, decorin competes with the natural ligand of EGFR, the epidermal growth factor (EGF), and the decorin-EGFR interaction results in internalization and degradation of the receptor via caveolar endocytosis, thus controlling tumor growth." (PMID 34917515, 2021). "In May 2020, treatment with nivolumab in combination with ipilimumab was approved for first-line treatment of patients with metastatic or recurrent NSCLC with no EGFR or ALK genomic tumor aberrations." (PMID 33677681, 2021). "The role of ubiquitination or deubiquitination in the sorting of receptor tyrosine kinases could be different in the physiological cellular process from that in pathological status (normal cell and tumor cell), which might lead to the controversial interpretation of STAMBP on EGFR regulation." (PMID 34102455, 2021). "Primary resistance to CTX is mainly due to aberrations in the KRAS, NRAS, and EGFR genes, which are often found in other cancer backgrounds, including colorectal cancer (CRC) and non-small cell lung cancer (NSCLC) but are uncommon in HNSCC tumours in CTX-naïve patients." (PMID 35008337, 2021). "As above, nonneoplastic colon tissue from tumor-free and tumor-bearing Apc+/Min-FCCC mice were evaluated for perturbations in processes associated with early tumorigenesis, including cellular proliferation, stemness, and EGFR and inflammatory signaling." (PMID 34513688, 2021). "Without the use of TKIs specifically targeting mutant EGFR, an increase mutant burden may not indicate treatment resistance in the tumor." (PMID 34692681, 2021). "This could also indicate a higher apoptotic activity in tumor cells with EGFR-amplification regardless of the MGMT-methylation status." (PMID 34298788, 2021). "The proposed GE11-CUR/ICG-LPs could not only actively target EGFR overexpressed cancer cells but also enable selective drug release controlled by NIR light, to significantly enhance the drug concentration at tumor sites, which could significantly reduce the off-target effects of CUR." (PMID 33868396, 2021). "In conclusion, these findings suggested that the lack of efficacy of ICI treatment in cancers expressing mutant forms of the EGFR may not depend on an enhanced expansion of Treg populations in EGFR overexpressing tumours." (PMID 35052732, 2021). "Researchers found that the expression of HE4 decreased after inhibition of HIF1-α expression or treated with HIF1-α inhibitor in tumor cells; HE4 could co-immunoprecipitate and co-locate with EGFR, and the interaction between HE4 and EGFR was enhanced after upregulation of HE4 expression." (PMID 35003362, 2021). "This requirement is more difficult to implement in clinical setting as it requires repeated tumor biopsies or reliable surrogate biomarkers (for example, analysis of hair follicles biopsies for EGFR phosphorylation and GLI levels to control pharmacodynamics of EGFR and Hedgehog inhibitors)." (PMID 33668112, 2021). "Meanwhile, when the false negative results due to low sensitivity come from low tumor content, trimming or macro‐ and microdissection may be useful to eliminate nontumor cells, and EGFR‐TKI would be effective on the tumors." (PMID 33314600, 2021). "Hence, the impact of BCA2 on NF-κB and IRF1, together with its roles in promoting the degradation of EGFR and c-Myc, suggests that BCA2 may play a tumor suppressive role." (PMID 34589482, 2021).
tumor (continued). "Furthermore, we found the disappearance of TFH–B and TRM–B interactions mediated by the CXCL13–CXCR5 axis in EGFR-MT tumors, which may negatively affect the formation of TLS in the tumor." (PMID 34663810, 2021). "No benefit of anti-EGFR was observed in right-sided CMS2/3 tumours." (PMID 34253874, 2021). "The killing of tumour cells was EGFR-specific and did not occur in the absence of EGFR expression." (PMID 33686177, 2021). "In line, the between‐group difference of tumor cell lysis was 7.4% (95%CI = −9.1;23.9, p = 0.34), and 13.7% (95%CI = −10.1;37.5, p = 0.23) in favor of the exercise group in the presence or absence of EGFR mAb, respectively." (PMID 34110712, 2021). "Even tumours with non-detectable EGFR expression responded well to treatment." (PMID 35052732, 2021). "In vivo, LR004-VC-MMAE inhibited tumor growth and even achieved complete regression in TNBC xenograft models, which further indicated that LR004-VC-MMAE may represent a promising therapeutic candidate against EGFR-overexpressing TNBC." (PMID 34879870, 2021). "Furthermore, our data demonstrated that the tumor suppressor microRNA-30c serves as another negative regulator of cCSC clustering and lung metastasis by targeting CD44 as well as its downstream effector EGFR." (PMID 33995681, 2021). "EGFR is expressed in tumor and non-tumor cells in the tumor microenvironment (TME)." (PMID 34950031, 2021). "CBD suppresses the activation of the EGF/EGFR signaling pathway and its downstream targets Akt, ERK and NF-κB in multiple tumor cells, which demonstrates that there might be a potential role for CBD to interfere in the cross-talk between inflammation, cell survival and tumor proliferation." (PMID 33921049, 2021). "Stereotactic ablative radiotherapy and stereotactic body radiotherapy to the primary tumour or metastases combined with EGFR-TKIs or first-line chemotherapy (for patients without EGFR mutations) significantly prolonged PFS and OS in patients with oligometastatic NSCLC." (PMID 34631535, 2021). "Third, other predictive biomarkers, such as radiomics features, carcinoembryonic antigen (CEA), cytokeratin 19 fragment (CYFRA21-1), epidermal growth factor receptor (EGFR), circulating tumor cells, and circulating cell-free DNA were not analyzed in the current study." (PMID 33292228, 2020). "Liquid biopsy for detecting plasma circulating tumor DNA (ctDNA) has entered clinical practice in NSCLC for detection of EGFR mutations either at baseline in patients with no available tissue for tumor genotyping or at disease progression after 1st/2nd generation EGFR TKIs." (PMID 32093010, 2020). "In addition to the formation of heterodimers within the HER-family there is also a cross talk between EGFR and other receptor tyrosine kinases such as the insulin like growth factor 1 receptor (IGF-1R), which is also involved in tumor development and progression." (PMID 32903756, 2020). "Taken together, the positive feedback loop between EGF/EGFR and UPR may cooperate for the survival of cancer cells in hazardous microenvironments and the stimulation of tumor angiogenesis, ultimately resulting in tumor relapse." (PMID 32630838, 2020). "In case 1, in the absence of tumor tissue biopsy, the presence of a BRAF mutation in cfDNA might have been interpreted as an underlying resistance mechanism to the EGFR inhibition." (PMID 33207619, 2020). "According to the blood CEA values and CT scan, the tumor acquired resistance to anti-EGFR treatment within 9 months and plasma-Seq revealed a novel focal amplification on 17q12, including ERBB2, which represents an established mechanism of resistance to anti-EGFR therapy." (PMID 32087735, 2020). "Remarkably, tumor EGFR protein expression has no direct relationship with drug efficacy." (PMID 31705176, 2020).